TNF (tumor necrosis factor)
Diseases named in the same sentence as TNF in open-access papers (continued):
Sharing a sentence is not in itself a finding about the gene and the disease.
gastric cancer (continued). "Thus, strong inducers of TNF-α in H. pylori act as tumor promoters in H. pylori-induced gastric cancer." (PMID 33804551, 2021). "In order to inspect the link between PTX3 and TNF-α in gastric cancer, we established that exogenous TNF-α might directly influence the manifestation of the PTX3 in the BGC-823 as well as SGC-7901 cells." (PMID 32194791, 2020). "We found MK2 expression to be linked to gastric cancer metastasis and nine significant cytokine associations, including MK2-dowstream cytokines, IL-1β, IL-6, and TNFα along with other previously unrecognized cytokines linked to MK2; G-CSF, GM-CSF, Mip-1β, IFN-α, MCP-1, and IL-2." (PMID 32216812, 2020). "Furthermore, PTX3 controlled the capability of cell migration, invasion as well as epithelial-mesenchymal transition (EMT) in gastric cancer cell lines mediated by TNF-α." (PMID 32194791, 2020). "In this study including 140 patients with gastric cancer receiving EN and probiotics for 8 days, the decrease in the incidence of diarrhoea and reduction of the pro-inflammatory cytokines level (IL-6, IL-8, and TNF-α) in the postoperative period were reported." (PMID 32917221, 2020). "Similarly, a previous study indicated that tumor necrosis factor-α-induced matrix metallopeptidase-9 secretion from mesothelial cells promoted the metastatic dissemination of gastric cancer cells." (PMID 32139657, 2020). "We infer the correlation between PTX3 and TNF-α during the progress of gastric cancer cells, which provides a foundation of TNF-α could regulate PTX3 in a negative way in vitro as well as in vivo." (PMID 32194791, 2020). "We then sought to investigate whether celastrol mediated inflammation by targeting BGN in gastric cancer cells; we evaluated the secretion of pro-inflammatory cytokine TNF-α and IL-8." (PMID 31739592, 2019). "We next examined whether TNF-α signaling increases the ROS level in gastric cancer cells by induction of NOXO1 expression." (PMID 30700829, 2019). "Some researchers also demonstrated that TNFα activates Parkin-dependent mitophagy to block mitochondrial apoptosis in gastric cancer cells, while a very recent study demonstrated that Roc-A enhanced natural killer (NK) cell-mediated lysis through inhibition of autophagy." (PMID 31551778, 2019). "We next examined the mechanism of the NOXO1 induction by TNF-α using human gastric cancer cells." (PMID 30700829, 2019). "For instance, TNFα induced apoptosis in human gastric cancer cells." (PMID 31637258, 2019). "Furthermore, expression of NOXO1 in human gastric cancer was positively correlated with those of TNF-α significantly." (PMID 30700829, 2019). "These experiments demonstrated that ALA inhibited both endogenous MUC4 and MUC4 induced by TNF-α in gastric cancer cells, which may contribute to its inhibition on gastric cancer." (PMID 31915505, 2019). "Taken together, ALA inhibits TNF-α-induced MUC4 in gastric cancer cells." (PMID 31915505, 2019). "Furthermore, the supernatant from gastric cancer cells induced IL-1β and TNFα expression in neutrophils and prolonged the half-life of neutrophils." (PMID 30292233, 2018). "We did not observe any remarkable association between TNF-α -1031 in gastric cancer patients and the healthy control group." (PMID 29118938, 2017). "IL-6 and TNF are expressed at high levels in human gastric cancer samples." (PMID 28350359, 2017). "TNF-α expression significantly increases in the sera of the patients with advanced gastric cancer." (PMID 29118938, 2017). "Additionally, upregulation through polymorphisms of the proinflammatory cytokines, tumor necrosis factor (TNF), and interleukin-1 (IL-1) has been associated with poor prognoses and disease severity in non-Hodgkin's lymphoma and gastric cancer, respectively." (PMID 26425120, 2015).
gastric cancer (continued). "Recently, in addition to some reports that miR-19a represses the expression of cell signaling pathway genes such as PTEN or TNF-α, the overexpression of miR-19a in gastric cancer has been demonstrated to promote the epithelial–mesenchymal transition by activating the PI3K/AKT pathway." (PMID 26367773, 2015). "Thus, the aim of the present work was to study the frequency of SNPs in TNF-α gene in Moroccan patients with gastritis, ulcer, and gastric cancer." (PMID 26504356, 2015). "TGFβ could sensitize gastric carcinoma cells to TNFα-induced apoptosis where TGFβ is responsible for Smad3-induced Bim transcription and TNFα to JNK-mediated stabilization of the Bim protein." (PMID 26405162, 2015). "IL-6 and TNF-α were found to be expressed at high levels in human gastric cancer samples." (PMID 23117246, 2013). "Moreover, suppression of OLFM4 enhances caspase-3 dependent apoptosis in response to H2O2 or TNF α in human gastric cancer cells." (PMID 22471589, 2012). "The anti-inflammatory effects of FFKSIL may be related to IgA, IgM, IgG, IL-6 and TNF-α production and IL-2, IL-4 and IL-10 reduction in gastric cancer rats." (PMID 22728348, 2012). "For example, TNF-α-308 G/A in the promoter of TNF-α has been reported to be associated with higher expression levels of TNF-α and thus susceptibility to numerous cancers, including cancers of the stomach, breasts, oral cavity, bladder and lung." (PMID 21995493, 2011). "In fact, it had been reported that cagA of H. pylori could induce TNF-α in gastric cancer biopsy specimens." (PMID 20699000, 2010). "TNF-α is involved in the upregulation of CXCR4 expression in gastric cancer induced by H. pylori." (PMID 20699000, 2010). "Haplotype-pairs formed with TNF-α-1031, -863 and -857 were associated with a significantly greater increased risk for gastric cancer only among smokers but not among non-smokers." (PMID 19615068, 2009). "In addition, TNF-α-induced ERK phosphorylation was significantly decreased in SNU216 gastric cancer cells by silibinin treatment." (PMID 19924065, 2009). "This supports our conclusion that the interaction between the TNF gene and smoking may play a crucial role in the etiology of gastric cancer." (PMID 19615068, 2009). "This study demonstrates that TNF-α-857 C/T polymorphism may play an independent role in gastric carcinogenesis and the gene-gene interaction of TNF also affects gastric cancer development." (PMID 19615068, 2009). "SNP-SNP interaction in the TNF gene including TNF-α-857 C/T or TNF-α-1031 T/C genetic variant was associated with a risk for gastric cancer among smokers but not among non-smokers." (PMID 19615068, 2009). "In addition to polymorphisms in interleukin genes, the polymorphisms in the promoter region of tumour-necrosis factor-A (TNF-A) gene have been extensively studied in relation to gastric cancer." (PMID 18319718, 2008). "Similarly, contrasting roles for PTX3 have been observed in gastric cancer under TNF-α stimulation." (PMID 41479916, 2025). "This underscores that TNF-α’s associations may be strongest with markers that are broadly relevant across gastric cancers (CEA, CA19-9, CA72-4) rather than those confined to special subtypes." (PMID 40299527, 2025). "Similarly, we also see an induction of high CXCL8 by TNFα, which promotes neutrophil migration into the TME, and is thought to promote tumour progression and CXCL8 expressing CAFs are associated poor prognosis in gastric cancer." (PMID 39743376, 2025). "One plausible explanation is that intestinal-type gastric cancers often arise on a background of chronic inflammation (e.g., long-standing H. pylori gastritis), which could prime the tumor microenvironment for higher TNF-α production." (PMID 40299527, 2025). "Furthermore, neutralizing TNF-α with adalimumab could reduce coculture-induced nuclear translocation of NF-κB, suggesting the involvement of TNF-α in the interaction between gastric cancer cells and CD204+ M2-like TAMs." (PMID 38175202, 2024).
gastric cancer (continued). "The genes targeted by AMK in the context of gastric cancer include apoptosis regulator Bcl-2 (BCL2), catenin beta 1 (CTNNB1), B-cell stimulatory factor 2 (IL6), mutated in multiple advanced cancers 1 (PTEN), proto-oncogene (SRC), and tumor necrosis factor ligand member 2 (TNF)." (PMID 38612999, 2024). "Therefore, TNF-alpha is the most studied marker in gastric cancer, and many studies are being conducted on the development of gastric cancer and the relationship with other gastric cancer biomarkers." (PMID 38612999, 2024). "In addition to the anti-inflammatory effects of PF treatments by the inhibition of IL-1β, IL-6, and TNF-α on LPS-treated Raw264.7 cells, the current study shows that PF treatments decreased tumor volume and induced cytotoxicity in gastric cancer cells in vivo and in vitro." (PMID 38140352, 2023). "Whereas more frequent HLA-G expression was observed in patients with advanced stages of gastric cancer, lymph node involvement, or advanced T-stage, affecting the prognosis of gastric cancer patients, which may be related to the induction of high TNF-α expression by HLA-G." (PMID 37533569, 2023). "In the present study, PF treatments inhibited inflammatory markers such as TNF-α, IL-6, and IL-1β in LPS-treated Raw264.7 cells and induced apoptotic cell death by activating the ER stress signaling pathway and releasing intracellular ROS in gastric cancer cells." (PMID 38140352, 2023). "Thus, we excluded the role of XIAP in TP/TNF-α–induced apoptosis in gastric cancer and supposed that FLIP might play an essential role in TP/TNF-α–induced apoptosis in AGS and MKN45 cells." (PMID 36110523, 2022). "Moreover, once the carcinogenesis is initiated, the process is maintained due to the persistent activation of this signaling, along with TNF-α–NF-κB, resulting in the subsequent activation of intrinsic cytokine signaling for promoting gastric cancer cell growth." (PMID 35884067, 2022). "However, the predictive value of TNF-α levels for the severity of gastric cancer is controversial." (PMID 35892729, 2022). "Moreover, recent studies have shown that NR4A1 induces TNFα-mediated apoptosis sensitivity in human gastric cancer and improves cisplatin resistance in ovarian cancer, supporting that NR4A1 plays a crucial role in drug therapy sensitivity in a variety of tumor models." (PMID 34209871, 2021). "In the analysis of key genes of prognostic value in gastric cancer, Jiang indicated that Tyrobp is related to positive macrophage activation, tumor necrosis factor (TNF) production regulation and tolerance induction regulation, and may play an immunosuppressive role in CD8 T cells and macrophages." (PMID 37786556, 2021). "Importantly, recent studies have documented, while responding to an H. pylori infection, the infiltration of a unique subset of PMN-MDSCs which express MIR130B, an endogenous short noncoding RNA, as well as TNF-α, known to contribute to immunotherapy-resistant gastric cancer." (PMID 34944780, 2021). "Furthermore, TNF-α polymorphisms, especially TNF-α-308 G/A, are linked to a substantial increase in risk of developing gastric cancer, although the mechanism is unknown." (PMID 34944729, 2021). "Additionally, overexpression of PTX3 might decrease the gastric carcinoma migration as well as invasion capacity mediated by TNF-α according to our data." (PMID 32194791, 2020). "Furthermore, the inhibition of TNF via ADAM17 alleviates cytokine-mediated inflammation, reduces the risk of gastric cancer and may also prevent hypochlorhydria." (PMID 31636639, 2019). "We sought to determine whether ALA can suppress TNF-α-induced MUC4 in human gastric cancer; to this end, we pretreated AGS, BGC-823, and MKN-28 cells with the indicated concentrations of ALA for 24 h followed by exposure of the cells with 20 ng/mL TNF-α for 4 h." (PMID 31915505, 2019).
gastric cancer (continued). "In addition, IL-1B and TNF-α levels have been shown to increase in H. pylori-infected Pol β mutant mouse gastric mucosa, which may stimulate gastric dysplasia and gastric cancer development." (PMID 31216714, 2019). "TNF-α could activate Wnt/β-catenin via Akt-GSK3β signaling in gastric cancer." (PMID 26417932, 2015). "H. pylori and TNF-α could induce Wnt10a and Wnt10b expression in gastric cancer cells." (PMID 26417932, 2015). "Moreover, some meta-analysis summarizing all these results studies, identified the TNF-α polymorphisms as a risk factor for gastric cancer in Caucasian populations, but not in Asian populations." (PMID 26504356, 2015). "TNF cytokine may interact with cigarette smoking to promote gastric cancer development." (PMID 19615068, 2009). "Moreover, it has been shown recently that activated macrophages may activate Wnt signalling in gastric cancer epithelial cells via TNF-alpha thus contributing to tumour development." (PMID 19732435, 2009). "Also, we were not able to clearly evaluate TNF-α-308 AA polymorphism and gastric cancer because none of our gastric cancer cases had the TNF-α-308 AA polymorphism." (PMID 19615068, 2009). "In our study, we observed that TFF1 expression was downregulated in gastric cancer-derived KATO III cells upon exposure to IFNγ alone, whereas in primary human gastric mucosoids, its repression required a combination of TNF-α, IL-1β, and IFNγ." (PMID 41573568, 2025). "In patients with gastric cancer at stages I, II, and III of the disease, there is an increase in such proinflammatory cytokines as TNF-α, IL-2, IL-8, TNF-β, IL-17A, and IL-6, as well as a decrease in IFNγ." (PMID 40806737, 2025). "PTX3 is less expressed in gastric cancer, but overexpression of PTX3 inhibits gastric cancer cell migration, invasion, and EMT, which can be reversed by TNF-α treatment." (PMID 41479916, 2025). "The present study aimed to investigate the correlations between plasma TNF-α levels and established tumor markers (AFP, CEA, CA72-4, and CA19-9) in gastric cancer patients, with particular attention to how these relationships vary across disease stages." (PMID 40299527, 2025). "Studies have shown that down-regulating IL-6, IL-17RA and tumor necrosis factor-alpha (TNF-α) levels can effectively improve the pathological changes of gastric mucosa tissue and hinder the development of PLGC into gastric cancer." (PMID 41284643, 2025). "Consistently, serum levels of IL-6 and TNF-α significantly increased with miR-3613-5p overexpression, indicating that miR-3613-5p promotes the progression from CAG to gastric cancer in mice." (PMID 40255569, 2025). "In contrast, gastric cancer cell-derived exosomes enriched with THBS1 enhanced Vγ9Vδ2 T cell cytotoxicity against gastric cancer, increasing the production of IFN-γ, TNF-α, perforin, and granzyme B both in vivo and in vitro." (PMID 39748921, 2024). "To explore the specific mechanism by which LDN reduces postoperative complications, we conducted scientific research on gastric cancer tissue and analysed the expression levels of TLR4, IL-6 and TNF-α." (PMID 38720250, 2024). "CD19+CD24hiCD38hi cells in gastric cancer are the primary source of IL-10 and can significantly inhibit the secretion of IFN-γ and TNF-α by CD4+ T cells." (PMID 39840050, 2024). "The TNF-α-ERK-VGLL1-TEAD4 pathway upregulates integrin αV expression, increasing the adhesion and invasive ability of gastric cancer cells." (PMID 39228892, 2024). "In our study, TNF, IL6, BCL2, PTEN, CTNNB1, and SRC are presented as common target genes between gastric cancer and AMK." (PMID 38612999, 2024). "Using this organoid system, we provide evidence against the signaling pathways of TNFα and HDGF to develop gastric cancer." (PMID 37047540, 2023). "To clarify the role of HDGF and TNFα secreted from H. pylori, we prepared recombinant proteins of HDGF and TNFα and added them into the organoid cultures, and the cytotoxicity of gastric cancer organoids." (PMID 37047540, 2023).
gastric cancer (continued). "Elevated levels of inflammatory markers, including interleukin-1 beta (IL-1β), C-reactive protein (CRP), and tumor necrosis factor-alpha (TNF-β), have been identified in CP and gastric cancer." (PMID 37568790, 2023). "PADI4 plays a role in gastric cancer by upregulating the expression of C-X-C motif chemokine receptor 2 (CXCR2), keratin 14 (KRT14), and tumor necrosis factor (TNF-α)." (PMID 37804426, 2023). "In gastric cancer, we confirmed that VGLL1, which has a similar structure to TAZ, binds with TEAD4 to the integrin αV promoter in the presence of TNF-α." (PMID 36613819, 2022). "The expression level of TXNIP was meaningfully lower in gastric cancer (GC) tissues compared with normal tissues, TXNIP negatively regulates helicobacter pylor-related GC by inhibiting TNFα-induced activation of NF-κB signaling pathway." (PMID 35450411, 2022). "A number of DNA polymorphisms in TNF and STAT controlled cytokine genes have been mapped, including IL-1β, IL-1R, -8, -6, -17A, 17F, -22, that may mediate differences in response to chronic H. pylori infection and therefore risk for gastric cancer and reviewed." (PMID 35844493, 2022). "In conclusion, our study demonstrated that TNFR1–ERK–VGLL1 signaling activated by TNF-α secreted from RAW264.7 cells increased integrin αV expression, thereby increasing the adhesion and invasive ability of gastric cancer cells." (PMID 36613819, 2022). "It has been shown that IL-1β, IL-33, IL-23, and TNF-α increase migration, invasion, and epithelial-mesenchymal transition (EMT) in gastric cancer cell lines AGS, MKN-45, MGC-803, BGC-823, and SGC-7091, cellular processes that are related to tumor progression." (PMID 35955936, 2022). "Activation of the TNF/TNFR2 pathway has been established as a critical bio-marker of several cancers including oral and gastric cancers." (PMID 35844493, 2022). "Gastric cancer (GC)‐derived TNF‐α and IL‐1β enhanced the motility of CAFs to induce GC metastases." (PMID 34459125, 2021). "In gastric cancer cells, it was found that depletion of the OLFM4 gene inhibited cell growth and increased sensitization to hydrogen peroxide, and TNFα induced apoptosis." (PMID 34912753, 2021). "Regarding TNFα involvement in resistance to therapy, we have described TNFα involvement in trastuzumab resistance in HER2+ breast and gastric cancer." (PMID 33540543, 2021). "Okadaic acid stimulated gastric cancer development in rats treated with MNNG, along with strong induction of TNF-α in the stomach." (PMID 33804551, 2021). "Our results indicated that z-guggulsterone dose-dependently raised the level of TNF-α and reduced the levels of TGF-β1 and VEGF in gastric cancer cells." (PMID 33488300, 2021). "P65, an anti-apoptosis regulator, one of the molecules downstream TNFα, was reduced once ADAM17 downregulated, suggesting that ADAM17 promoted the development of gastric cancer through the regulation of TNFα signaling pathway." (PMID 34182543, 2021). "In another study, full-length human TNF-α was transduced into MSCs; after subcutaneous injection of SGC-7901 (gastric cancer cells) and UCMSC-TNF-α in the mouse model, tumor growth was significantly decreased." (PMID 34249257, 2021). "Since PTX3 can be regulated by TNF-α, we believed that PTX3 contributes in gastric carcinoma advancement facilitated by exogenous TNF-α." (PMID 32194791, 2020). "We also found that NF-κB directly regulated NOXO1 expression in TNF-α-stimulated gastric cancer cells, suggesting that inflammation induces NOX1 complex activation through TNF-α/NF-κB pathway." (PMID 30700829, 2019). "This event may be triggered by various stimuli, including cytokines such as tumor necrosis factor (TNF), interleukin-1 (IL-1), as well as bacterial and viral products such as lipopolysaccharide (LPS), such as that produced by Helicobacter pylori in the case of gastric cancer." (PMID 30487159, 2019).